UBE2C (ubiquitin conjugating enzyme E2 C)
Diseases named in the same sentence as UBE2C in open-access papers (continued):
Sharing a sentence is not in itself a finding about the gene and the disease.
cancer (continued). "UBE2C elevation is observed in lung, bladder and ovarian cancers, underscoring its potential as a cancer biomarker." (PMID 25734985, 2015). "We further demonstrated that UBE2C shRNA triggered cell death by activating an apoptosis pathway, which suggested the potential target of UBE2C for therapeutic intervention in cancer." (PMID 24699941, 2014). "Downregulating UBE2C expression with siRNA oligonucleotides inhibited cancer cell proliferation, arrested cells at S and G/M phases of the cell cycle and led to cell death." (PMID 24699941, 2014). "Recent data has shown that aberrantly high expression of UBE2C contributes to tumorigenesis, and has revealed its potential as a biomarker for cancer prognosis." (PMID 23587173, 2013). "Overexpression of ubiquitin-conjugating enzyme 2C (UBE2C) has been detected in many types of human cancers, and is correlated with tumor malignancy." (PMID 23587173, 2013). "Using Immunohistochemistry, we showed over-expression of MMP3, UBE2C and p16 in cancers compared to normal cervical epithelium and varying grades of dysplasia." (PMID 21338529, 2011). "This gene is also functionally related to the known cancer gene Ube2c, which also was discovered by RIT." (PMID 17490475, 2007). "Targeting this enzyme could help to inhibit cancer cell division and inhibitors of UBE2C could serve as novel chemotherapeutic agents to prevent tumour growth." (PMID 41492994, 2026). "The ERK signaling pathway was stimulated and cancer cell growth was aided by UBE2C overexpression." (PMID 40224213, 2025). "Paired analysis of patient samples further demonstrated that UBE2C is highly expressed across various cancer types, suggesting that UBE2C could function as a TSA." (PMID 40135850, 2025). "Our research confirmed that UBE2C could serve as a biomarker for the diagnosis, treatment and prognosis of pan-cancers including LUAD." (PMID 38370368, 2024). "By q‐value cutoff = 0.01 and |LogFC| cutoff = 1, UBE2C gene was upregulated in 28 types of cancer." (PMID 38577722, 2024). "High UBE2C protein expression levels were seen in all cancer types." (PMID 38577722, 2024). "In addition, UBE2C has demonstrated to play a critical role in modulation of the immune response of human cancers." (PMID 38075202, 2024). "Also, in most of the cancers, there was a significant correlation between UBE2C gene expression and CD96, CD274, CSF1R, KDR, and PDCD1LG2." (PMID 38577722, 2024). "We identified 10 miRNAs as regulatory mediators that could target UBE2C and act as crucial determinants of cancer progression." (PMID 38577722, 2024). "As a cancer suppressor gene, UBE2C importantly regulates the cell cycle." (PMID 39935706, 2024). "Furthermore, UBE2C is intimately involved in a variety of signaling pathways in multiple cancers, including the WNT/β-catenin pathway." (PMID 39479352, 2024). "Also, in most of the cancers, there was a significant correlation between UBE2C gene expression and C10orf54, CXCL12, IL6R, MICB, PVR, THEM173, and TNFSF13." (PMID 38577722, 2024). "Also, “Expression Analysis‐Box Plots” module showed that by p‐value cutoff = 0.01 and |LogFC| cutoff = 1, among 31 types of cancers, UBE2C was upregulated in 30 cancers." (PMID 38577722, 2024). "Furthermore, the correlation of UBE2C expression with clinical outcomes confirmed that UBE2C overexpression results in poor prognosis, worse overall survival, and disease‐free survival in many cancers." (PMID 38577722, 2024). "Intersectional analysis identified UBE2C as a common DEG between all 28 types of studied cancers." (PMID 38577722, 2024). "Moreover, it has been demonstrated that UBE2C deregulation plays an important role in the development and malignant progression of various cancers." (PMID 38637730, 2024). "Several reports indicated that UBE2C was highly expressed in various cancers." (PMID 38637730, 2024). "Pan‐cancer prognostic value of UBE2C was investigated using dataset from GEPIA2." (PMID 38577722, 2024).
cancer (continued). "Furthermore, the GEPIA2 database was utilized to examine the prognostic implications of UBE2C in various types of cancer." (PMID 38370368, 2024). "UBE2C co‐expressed genes in different types of cancer were retrieved using LinkedOmics." (PMID 38577722, 2024). "Also, UBE2C can be a diagnostic factor in CESC, CHOL, GBM, and UCS with AUC = 100% and diagnose 19 cancer types with AUC ≥90%." (PMID 38577722, 2024). "CDCA3 was found as a UBE2C correlated gene, which is common in 30 types of TCGA cancers." (PMID 38577722, 2024). "Consistently, a recent study reported that detecting of UBE2C expression level through IHC sections could be an indicator of polyploidy in cancer tissue, allowing discrimination of aggressive subsets of HCC." (PMID 38577722, 2024). "UBE2C protein level was gradually elevated from grade 1 to grade 3, indicating that UBE2C protein may be a specific biomarker for UCEC cancer cell differentiation." (PMID 37803076, 2023). "In addition, 13 UBRs were deregulated in 20 or more cancer types, of which UHRF1 and UBE2C were both deregulated in 25 cancer types." (PMID 37667177, 2023). "A study based on our previously published research suggested that UBE2C may promote the development of pan-cancer by influencing cell cycle through the regulation of the G1/S-phase transition." (PMID 37958642, 2023). "Due to its role in promoting cancer migration and invasion, UBE2C could be an effective biomarker for UCEC metastatic prediction and monitor." (PMID 37803076, 2023). "And the pan-cancer analysis suggested that UBE2C is an oncogenic gene in various tumors." (PMID 37535572, 2023). "The results suggested that LUAD might originate from Clara and AT2 cells, eventually evolving into the UBE2C+ cancer cell subpopulation, in which UBE2C mediates the proliferation and metastasis of tumor cells." (PMID 37592342, 2023). "Our findings demonstrate that the pharmacological co-inhibition of PLK1 and ACLY significantly suppresses pan-cancer cell proliferation compared to single-agent treatment and that this combination downregulated UBE2C mRNA and protein expression, which revealed a novel potential molecular mechanism." (PMID 37958642, 2023). "However, we found evidence of decreased dissemination of cancer cells with UBE2C silencing to the spinal cord meninges." (PMID 37215954, 2023). "This notwithstanding, we have shown that UBE2C is a relevant player in brain metastatic disease, especially relevant for leptomeningeal dissemination, and that it can be used as a prognostic marker in cancer patients with this condition." (PMID 37215954, 2023). "Considering the analysis results of the transcriptional data of various cancers in the TCGA database, it is suggested that UBE2C may be a downstream gene that is co-regulated by KAT2A and E2F1." (PMID 36292703, 2022). "The oncogenic effect of UBE2C in human cancers has been revealed." (PMID 35332135, 2022). "As a result, the current data support an oncogenic function of UBE2C in pan-cancer tumorigenesis and may offer a new prognostic biomarker or therapeutic target for future development." (PMID 35804892, 2022). "Recent research has reported that UBE2C played an important role in the radiotherapy of malignant tumors, whose downregulation might increase the sensitivity of tumor cells." (PMID 36069832, 2022). "Based on these findings, LUAD may originate from both Clara cells and AT2 cells, and the UBE2C + cancer cell subpopulation is the terminal cell type of LUAD." (PMID 36434043, 2022). "These researches all revealed the oncogenic role of UBE2C involved in cancer progression." (PMID 35332135, 2022).
cancer (continued). "Additionally, the results from the CCK-8 assay showed that the proliferation of different cancer cell lines was markedly suppressed with knocking down UBE2C in MCF-7, 786-O, and NCI-H460 cells compared with the control group." (PMID 36292703, 2022). "The molecular mechanism underlying increased UBE2C gene expression in cancers is unclear and the relevant findings were not validated by experiments." (PMID 35804892, 2022). "Additionally, the pan-cancer analysis showed that UBE2C was overexpressed and hypomethylation in almost all cancer types and was related to poor prognoses for various cancers." (PMID 35804892, 2022). "Over-expression of UBE2C protein stimulates cell proliferation, may act as an important proto-oncogene and is found over-expressed in several cancers." (PMID 36293188, 2022). "For example, the UBE2C-u5 transcript showed significant upregulation in 11 different cancer types." (PMID 36357395, 2022). "Combining with the unfavorable prognostic role of UBE2C, it suggested that UBE2C may act as an oncogene in these cancers." (PMID 35332135, 2022). "This study revealed the common characteristics of KAT2A/E2F1/UBE2C and clarified the mechanism of this axis across pan-cancer through RNA-seq dada and in vitro experiments, which might shed light on pan-cancer treatment." (PMID 36292703, 2022). "Hypomethylated UBE2C might serve as a potential new pan-cancer biomarker for the prognosis and diagnosis of various types of cancers." (PMID 35804892, 2022). "Therefore, we conducted an integral analysis of the pan-cancer role of UBE2C with a variety of multibioinformatics tools, especially DNA methylation analysis." (PMID 35804892, 2022). "Gene UBE2C play a very critical function in the impact of cancer on the human body." (PMID 35571064, 2022). "This may result in the activation of cancer cell migration and invasion, which may explain the vital role of UBE2C in LVI and metastasis in BC." (PMID 35124721, 2022). "Recently, there was an article on the bioinformatics analysis of UBE2C in pan-cancer." (PMID 35804892, 2022). "In cancer cells, Ube2c inhibits apoptosis and enhances tumor growth." (PMID 36499442, 2022). "At present, several studies have reported the aberrant expression of UBE2C in human cancers." (PMID 35332135, 2022). "Thus, further studies are necessary to elucidate exactly how DNA methylation regulates UBE2C expression in cancers." (PMID 35804892, 2022). "Importantly, the overexpression of UBE2C was correlated with poor prognosis in a wide array of human cancers." (PMID 35804892, 2022). "Based on the ceRNA hypothesis, potential lncRNAs of the miR-140-3p/UBE2C axis may act as oncogenic lncRNAs in multiple cancer types." (PMID 34858987, 2021). "Overall, these results showed that UBE2C was upregulated in diverse human cancers." (PMID 34858987, 2021). "In summary, these results suggested that UBE2C was significantly related to drug sensitivity in different cancer cell lines and may be a promising therapeutic target for cancer patients." (PMID 34858987, 2021). "UBE2C overexpression has been confirmed in many kinds of cancer tissues." (PMID 34488675, 2021). "UBE2C, the ubiquitin-conjugating enzyme, is overexpressed in all 27 cancers." (PMID 34858479, 2021). "However, the prognosis and immunology role of UBE2C in human cancer have been an uncharted territory." (PMID 34858987, 2021). "In these cancers, the high UBE2C expression level meant high ImmuneScore only in KIRC." (PMID 34950739, 2021). "The results showed that UBE2C was a differentially expressed genes in 33 cancer types." (PMID 34950739, 2021). "We also found that UBE2C expression and different immune cell infiltrations could affect prognosis in different cancer types." (PMID 34858987, 2021).
cancer (continued). "UBE2C was differentially expressed in many cancer types and related to the pathogenesis and TME of many cancers, which might be a potential diagnostic and therapeutic biomarker." (PMID 34950739, 2021). "Furthermore, TME relevance analysis also indicated that the higher UBE2C expression level meant lower StromalScore and ImmuneScore levels in many cancer types like PAAD, UCEC, and BRCA." (PMID 34950739, 2021). "UBE2C restoration attenuated the MALAT1 knockdown-induced anti-cancer effects." (PMID 34257576, 2021). "For molecular subtypes, UBE2C displayed a unique expression pattern in cancer." (PMID 34858987, 2021). "A study have showed that UBE2C was related to the prognosis of many cancers." (PMID 34950739, 2021). "The results showed that UBE2C presents different expression patterns in pan-cancer." (PMID 34858987, 2021). "In our study, univariate Cox regression analysis in 33 cancer types also showed that UBE2C might be a prognostic biomarker in many cancers according to OS, DSS, DFI, and PFI." (PMID 34950739, 2021). "MiRNAs play a crucial role in the regulation of mRNA expression; according to the ceRNA theory, miRNA expression should be negatively correlated with mRNA expression, as UBE2C shows high expression in pan-cancer; therefore, regulatory miRNA expression should be lower in cancer." (PMID 34858987, 2021). "Previous studies indicated that UBE2C was related to the prognosis of many cancers." (PMID 34950739, 2021). "Ubiquitin-conjugating enzyme E2C (UBE2C) was differentially expressed in many cancer types." (PMID 34950739, 2021). "UBE2C, as an oncogene in these cancers, played a vital role in cancer development and therapy which indicated that it might be a potential effective therapeutic target for pan-cancer." (PMID 34950739, 2021). "Shared genes by all cancers with an adverse prognosis (high positive global meta-z-scores), such as MAD2L1, CCNB1, NUF2 and UBE2C, were associated with gene ontology (GO) enrichment analysis terms related to proliferation, replication and mitosis, similar to adult tumors." (PMID 33670534, 2021). "In this study, we utilized the public databases to analyze the expression and prognosis in pan-cancer; our results demonstrate that UBE2C was significantly upregulated in diverse cancers, and its high expression was closely related to the poor prognosis in diverse human cancers." (PMID 34858987, 2021). "UBE2C plays roles in some cancer stemness properties, such as drug resistance." (PMID 32899896, 2020). "It indicated that UBE2C overexpression positively correlated in several cancers." (PMID 33050659, 2020). "Compared to control cells, OSCC cells in which UBE2C was silenced showed decreased cell proliferation, migration/invasion and colony formation and they exhibited lower expression levels of the following cancer stemness markers—ALDH1/A2, CD44, CD166 and EpCAM." (PMID 32899896, 2020). "The high expression of UBE2C is found in the advanced stage of cancer, which might point out its involvement in cancer progression and invasion." (PMID 33050659, 2020). "Moreover, the expressions of UBE-2C protein or mRNA are aberrantly expressed in various cancer types that lead to poor clinical results." (PMID 33050659, 2020). "These included many cancer-associated genes such as AKT2, HRAS, TGFBI and UBE2C." (PMID 32437477, 2020). "UBE2C is involved in tumor progression and is considered a potential cancer biomarker." (PMID 32899896, 2020). "After analysis of multi-omic databases, it is speculated that UBE2C may affect the proliferation and survival of cancer cells." (PMID 33396624, 2020). "UBE2C is necessary for the destruction of mitotic cyclins and cell cycle progression, and may participate in the cancer progression." (PMID 31788359, 2019). "Some research has focussed the molecular mechanism of UBE2C deregulation in cancer." (PMID 30914455, 2019). "This indicates a possible involvement of UBE2C in the initiation of cancer." (PMID 31067633, 2019).
cancer (continued). "We showed that patients with higher expression of UBE2C had a shorter overall survival time and worse prognosis, and UBE2C higher-expression levels also resulted in worse DFS prognosis in many cancers, confirming that UBE2C overexpression results in poor clinical outcomes in many tumors." (PMID 31067633, 2019). "The oncogenic effect of UBE2C in several human cancers has been revealed." (PMID 30914455, 2019). "Importantly, our investigation showed that overexpression of UBE2C is a common feature of all 27 human cancers tested in this study, suggesting it acts as a proto-oncogene." (PMID 31067633, 2019). "We also identified genes with positive correlations with UBE2C in several cancers." (PMID 31067633, 2019). "For this cancer type, the UBE2C expression was more significant for post-menopause." (PMID 31067633, 2019). "The aberrantly high expression of UBE2C was reported in various cancers." (PMID 31681566, 2019). "UBE2C is one of the genes used in molecular classification in several types of cancers." (PMID 30116193, 2018). "Additionally, the ERK1/2 inhibitor U0126 was used to confirm the signaling pathway involved in UBE2C-mediated cancer progression." (PMID 30116193, 2018). "Therefore, in this study, we employed immunohistochemistry (IHC) and bioinformatics analysis guided by public databases containing data on gene expression in cancer to detect UBE2C expression in BRCA and adjacent tissues." (PMID 29021715, 2017). "Moreover, the cancer genome atlas (TCGA) database was employed to investigate the prognostic value of UBE2C in BRCA." (PMID 29021715, 2017). "Recently, E2 ubiquitin conjugating enzyme UBE2C was reported to be overexpressed in multiple human tumors and might be served as a potential cancer biomarker." (PMID 29137415, 2017). "Moreover, it has been already shown that high UBE2C expression is also related with a highly malignant phenotype and a poor survival suggesting its role in cancer progression." (PMID 27588470, 2016). "Furthermore, measurement of urinary UBE2C levels is a suitable noninvasive tool for discriminating BC patients from non-cancer patients with hematuria." (PMID 27528424, 2016). "Urinary levels of UBE2C could be used successfully to discriminate BC patients from non-cancer patients with hematuria (AUC, 0.839; sensitivity, 82.5%; and specificity, 76.2%)." (PMID 27528424, 2016). "In the carcinoma cells, UBE2C was found both in the nuclei and in the cytoplasm." (PMID 27556859, 2016). "The immunohistochemistry findings suggested that UBE2C expression might be associated with breast MC lesions, but we need a larger cohort to clearly define the implications of UBE2C expression in benign and malignant tumors." (PMID 24699941, 2014). "Development of a specific inhibitor of UBE2C would be a great benefit to cancer therapy." (PMID 24699941, 2014). "In addition, our retrovirus-delivered shRNA for UBE2C suppression would be advantageous in anti-cancer study in a xenograft model in vivo." (PMID 24699941, 2014). "Furthermore, inhibition of UBE2C expression induced by RNA interference significantly reduced the proliferation of cancer cells and enhanced cell apoptosis in vitro." (PMID 23587173, 2013). "Thus, UBE2C is not only essential for normal cell cycle regulation but also represents a key player in oncogenesis, making it a promising biomarker and therapeutic target in cancer treatment." (PMID 41492994, 2026). "Additionally, UBE2C expression showed a positive correlation with Th1 infiltration in 28 types of cancers, and a negative correlation with macrophage M2 infiltration in 24 types of cancers, excluding LGG and UVM." (PMID 38370368, 2024). "In summary, UBE2C can be a theranostic gene, which may serve as a reliable biomarker in diagnosing cancers, improving treatment responses and increasing the overall survival of cancer patients and can be a promising gene to be target by cancer drugs in the future." (PMID 38577722, 2024).